NTRK3 (neurotrophic receptor tyrosine kinase 3)
Diseases named in the same sentence as NTRK3 in open-access papers (continued):
Sharing a sentence is not in itself a finding about the gene and the disease.
papillary thyroid carcinoma (17 papers, 2014 to 2025). "ETV6::NTRK3 common in radiation-associated papillary carcinoma." (PMID 38108848, 2024). "Common in papillary carcinoma of children and young adults (NTRK3 fusion, ~ 15%; NTRK1 fusion, ~ 5%)." (PMID 38108848, 2024). "In this study, a dual NTRK3 fusion was identified by targeted RNA-Seq in a 47-year-old female patient with papillary thyroid carcinoma." (PMID 37188179, 2023). "We found a significant association between the localization of RET mutations and the expression of three genes: NNAT (suggested to be a tumour suppressor gene), CDC14B (involved in cell cycle control) and NTRK3 (tyrosine receptor kinase that undergoes rearrangement in papillary thyroid cancer)." (PMID 28181547, 2017).
colon cancer (15 papers, 2010 to 2024). "Somatic mutation of NTRK3 has been reported in human colon cancer, while methylation of EYA4 has been documented previously in ulcerative colitis-associated dysplasia and CRC." (PMID 20492682, 2010). "Taken together, these data provide support for the aberrant methylation of the NTRK3 promoter silencing NTRK3 expression in colon neoplasms." (PMID 23874207, 2013). "Reintroduction of NT-3 releases colon cancer cells from NTRK3-mediated apoptosis, which is consistent with NTRK3 being a dependence receptor in the colon." (PMID 23874207, 2013). "Through a genome-wide screen for methylated genes in colon cancers, we identified methylated NTRK3 in colon adenomas and adenocarcinomas." (PMID 23874207, 2013). "We also assessed the status of NTRK3 in a panel of colon cancer cell lines (N = 9) and found that all the cell lines had methylated NTRK3 using the 13.7% PMR threshold." (PMID 23874207, 2013). "Because NT-3 is expressed in the colon epithelium but not in colon neoplasms, our findings suggest that silencing of NTRK3 releases colon cancer cells from NTRK3-mediated apoptosis." (PMID 23874207, 2013). "In addition, METex14del occurs exclusively to ALK, ROS1, NTRK1, NTRK3 or RET fusions indicating METex14del is likely a driver mutation and defines a unique molecular subset of gastric and colon cancers." (PMID 26375439, 2015). "Therefore, our findings suggest that NTRK3 is the primary and perhaps only receptor for NT-3 in the colon and in colon neoplasms." (PMID 23874207, 2013). "Moreover, the expression of NTRK3 was significantly higher in the primary colon tumors that carry unmethylated NTRK3 compared to the tumors that carry methylated NTRK3." (PMID 23874207, 2013). "We next assessed the signaling pathways that are affected by NTRK3, which have been shown to include the MAPK/Erk, NF-κB and PI3K/Akt pathways, to determine if they may be mediating NTRK3 induced apoptosis in the colon cancer cell lines." (PMID 23874207, 2013). "With regards to the functional significance of this epigenetic alteration, we found that the aberrant methylation of NTRK3 suppressed NTRK3 expression, which suggested NTRK3 might act as a tumor suppressor gene in colon cancer." (PMID 23874207, 2013). "Finally, Ntrk3 is a potential tumor suppressor inactivated in colon cancer and acts as a dependence receptor, therefore its down-regulation in LSC GFP+ cells might create a clonal survival advantage in the absence of its ligand NT-3." (PMID 27081082, 2016). "The demonstration of NTRK3 as a potential conditional tumor suppressor gene in the colon suggests NTRK3 may be the latest member of a class of dependence receptors that suppress colon cancer formation." (PMID 23874207, 2013). "In light of the prior reports implicating a fusion gene involving NTRK3 affecting TGF-β signaling and TGF-β mediated cell behavior, we also assessed the TGF-β, BMP signaling and EMT markers in colon cancer cells after transfection with NTRK3." (PMID 23874207, 2013). "We identified the cg27034819–cg11525479 region within NTRK3 promoter as the most promising predictive marker for survival outcome, and it was validated in our CRC cohort and 23 TCGA cohorts including a colon cancer cohort, a rectal cancer cohort and 21 cohorts of other tumor types." (PMID 33593392, 2021). "Reconstitution of NTRK3 in the absence of NT-3, the ligand for NTRK3, induced caspase-related apoptosis and cell death in the colon cancer cell lines RKO, HT29 and HCT116." (PMID 23874207, 2013). "However, despite the potential for cross-talk, we did not observe any effects on colon cancer cells that lacked NTRK3 after being treated with NT-3." (PMID 23874207, 2013).
salivary gland tumors (13 papers, 2015 to 2024). "The ETV6::NTRK3 fusion – detected in a single patient with a salivary gland tumor – has been commonly reported by others." (PMID 38967220, 2024). "In the context of salivary gland tumors, ETV6::NTRK3 fusion is specific for secretory carcinoma (SC)." (PMID 37415052, 2023). "In the same line, a high-grade salivary gland tumor composed of expansile, centrally necrotic nests composed of AR-positive and S100-negative apocrine-type cells with an ETV6::NTRK3 fusion was recently interpreted as salivary duct carcinoma with an unusual genetic background." (PMID 37415052, 2023).
glioblastoma (10 papers, 2014 to 2024). The most malignant astrocytic tumor (WHO grade IV). "Finally, NTRK3 promoter methylation also predicted survival in other tumors, including pancreatic cancer, glioblastoma and stomach adenocarcinoma." (PMID 33593392, 2021). "In our analyses, NTRK3 hypermethylation was associated with worse survival in some tumors, such as CRC, kidney chromophobe, and pancreatic adenocarcinoma, but it is related to a better outcome in other tumors, including glioblastoma multiforme, skin Cutaneous Melanoma, and stomach adenocarcinoma." (PMID 33593392, 2021). "For example, among brain tumors, glioblastoma, pilocytic astrocytoma, and pontine glioma can show gene fusions involving NTRK2 or NTRK3." (PMID 32906676, 2020).
mesenchymal tumors (10 papers, 2020 to 2025). "Gene fusions involving the NTRK gene family (NTRK1, NTRK2, and NTRK3) are usually described in a broad spectrum of mesenchymal tumors." (PMID 37798904, 2024). "Fusions involving NTRK1, NTRK2, and NTRK3 are oncogenic drivers occurring in a spectrum of mesenchymal neoplasms ranging from benign to highly malignant tumors." (PMID 32860002, 2021). "To date, most of the fusions described in mesenchymal neoplasms involve NTRK1 and NTRK3 genes and include different fusion partner genes, most common being ETV6, LMNA, and TPM3." (PMID 32860002, 2021). "Thus, while ETV6::NTRK3 fusion identifies the homogeneous group of IF and the renal counterpart (cellular or mixed CMN), EGFR‐KDD mesenchymal neoplasms are a heterogeneous group of mesenchymal neoplasms which deserve further investigation." (PMID 40178433, 2025).
salivary gland carcinoma (10 papers, 2016 to 2025). A carcinoma that arises from the major or minor salivary glands. "A high prevalence of ETV6::NTRK3 in salivary gland carcinoma in the present study is probable as most head and neck cancers were identified as salivary gland carcinoma (72.7%) and the rest were unclassified." (PMID 38925616, 2024). "The patient with NSCLC harbored an SGCZ::NTRK3 fusion tumor, while the patient with salivary gland cancer harbored an ETV6::NTRK3 fusion." (PMID 38967220, 2024). "Other detected fusions were SGCZ::NTRK3 (NSCLC) and ETV6::NTRK3 (salivary gland cancer)." (PMID 38967220, 2024). "Salivary gland carcinomas share the same histological and immunohistochemical features as mammary gland secretory carcinomas, including mutated ETS 6 (ETV6) gene and translocation of neurotrophic receptor tyrosine kinase type 3 (NTRK3), which regulate cell growth and differentiation." (PMID 40391352, 2025). "ETV6::NTRK3 was the only NTRK fusion gene detected in head and neck cancer and is known to be common in salivary gland carcinoma." (PMID 38925616, 2024). "Additionally, fusions observed in other subtypes of salivary gland carcinoma, such as ETV6::NTRK3 and NCOA4::RET described in secretory carcinoma and intraductal carcinoma, respectively, have been reported in SDC without any histologic evidence of these other tumor types." (PMID 41357819, 2025).
schizophrenia (10 papers, 2010 to 2024). A major psychotic disorder characterized by abnormalities in the perception or expression of reality. "There is also evidence that polymorphisms in the human NTRK3 gene, coding for trkC, are involved in mood disorders, bipolar disorders and schizophrenia." (PMID 39194496, 2024). "Multiple pieces of evidence have linked CNTN2, CNTNAP2, GABBR2, and NTRK3 to neuropsychiatric disorders, including schizophrenia." (PMID 30323833, 2018). "Furthermore, it has been suggested that the NTRK3 gene influences hippocampal function and may modify the risk of schizophrenia." (PMID 21070662, 2010). "A reduction in transcript levels of NTRK3, also known as tyrosine kinase receptor C (trkC), has been observed in patients with schizophrenia." (PMID 38528588, 2024). "In the network, candidate genes with nominal significance such as ANKS1B, CNTN2, CNTNAP2, GABBR2, NCOR2, and NTRK3 also may be involved in the pathology of schizophrenia." (PMID 30323833, 2018). "Gene expression of NTRK3 has been reported to be reduced in patients with schizophrenia." (PMID 21070662, 2010).
gastric cancer (9 papers, 2020 to 2024). A primary or metastatic malignant neoplasm involving the stomach. "In gastric cancer, MIR4435-2HG has been shown to promote gastric cancer progression through the miR-497-5p/NTRK3 axis and the miR-138-5p/Sox4 axis." (PMID 35784328, 2022). "Hsa-circ-0009172 suppressed the expression of NTRK3 by acting as a sponge for miR-485-3p, which in turn inhibited the proliferation, invasion, and migration capabilities of gastric cancer cells, as well as the expression of epithelial-mesenchymal transition-related proteins." (PMID 39596658, 2024). "Therefore, a mechanistic study was conducted in NCI-N87 (high expression of NTRK1-3 but mutation of NTRK3), AGS (high expression of NTRK1-3) and MKN28 (low expression of NTRK1-3) gastric cancer cell lines." (PMID 35008821, 2021). "Finally, the role of mutated NTRK3 as target gene for treatment of non-small cell lung cancer is exploited by clinical trials, whereas targeting FGFR2 and EGFR in stomach cancer is considered promising for improving current strategies." (PMID 32111026, 2020).
lung adenocarcinoma (9 papers, 2014 to 2025). A carcinoma that arises from the lung and is characterized by the presence of malignant glandular epithelial cells. "Here, we report the first case of a female patient with a diagnosis of stage IV lung adenocarcinoma harboring the EML4::NTRK3 gene fusion, and successfully treated with entrectinib." (PMID 36419889, 2022). "As for the other reference genes such as ROS1, HER2, RET, MET, NTRK1, NTRK2, and NTRK3, our study did not identify mutations in these genes in patients with lung adenocarcinoma." (PMID 38828424, 2024). "Our primary screen generated a functionally annotated list of 28 genes that led to robust metastatic dissemination and merit further interrogation, including some that have been previously identified to be mutated in lung adenocarcinoma (GNAS, MAPK6, ACVR1B, FBXW7, NTRK3)." (PMID 30013058, 2018). "In this study, four key biomarkers closely related to mesenchymal stem cell proliferation/differentiation (MSCPD) were identified in lung adenocarcinoma (LUAD), namely MS4A2, IGSF10, NTRK3, and MFAP3L." (PMID 40598621, 2025).
Anxiety (8 papers, 2020 to 2025). Intense feelings of nervousness, tension, or panic often arise in response to interpersonal stresses. "These significant discoveries potentially open new directions in anxiety treatment, especially using NTRK3-targeting medication and hormonal approaches such as estradiol." (PMID 40508224, 2025). "For example, Ntrk3, Tnr, Cacna1h, Clstn2, and Rapgef2 were found to be involved in pathological processes of anxiety." (PMID 33431988, 2021). "Given several previous human genetic studies showing linkage of NTRK3 with anxiety-related disorders including panic disorder and OCD, and mood disorders including major depression, we further performed behavioral experiments to assess anxiety, avoidance and depression behaviors in TrkC KI mice." (PMID 39333774, 2024).
depression (8 papers, 2012 to 2024). "An association study of 15q25-26 for recurrent early onset depression showed nominal association with NTRK3 and the genes flanking ST8SIA2: SLCO3A1 and C15orf32; but not ST8SIA2 itself." (PMID 22693595, 2012). "In line with the neurotrophic hypothesis of depression, genes coding for members of the neurotrophic tyrosine receptor kinase family such as Ntrk2 and Ntrk3 were normalized by FLX action in a reverse direction compared to observation in rodent stress models of depression." (PMID 36362329, 2022).
hepatocellular carcinoma (8 papers, 2013 to 2025). A malignant tumor that arises from hepatocytes. "In hepatocellular carcinoma, miR-485-3p was shown to also promote proliferation and invasiveness by downregulation of NTRK3, which codes for the neurotrophic tyrosine kinase receptor type 3." (PMID 35954369, 2022). "Interestingly, in hepatocellular carcinoma, lnc-AGBL1-4 has been demonstrated to regulate the expression of NTRK3 by miR-128 and miR-485-3p to strengthen cell invasion and migration." (PMID 27916857, 2016).
mucoepidermoid carcinoma (8 papers, 2015 to 2026). A carcinoma morphologically characterized the presence of cuboidal mucous cells, goblet-like mucous cells, squamoid cells, cystic changes, and a fibrotic stromal formation. "In our patient pool, the rearrangement of the NTRK3 gene was found in four patients: two diagnosed with mucoepidermoid carcinoma and two with acinic cell carcinoma." (PMID 39376339, 2024). "We identified NTRK3 gene rearrangements in four patients (11%), two of whom had mucoepidermoid carcinoma, and the remaining two had acinic cell carcinoma." (PMID 39376339, 2024). "In both mucoepidermoid carcinomas, the rearrangement of MALM2 was found in addition to that of NTRK3, while in only one of the two also of EWRS1." (PMID 39376339, 2024). "The OS and PFS of patients with mucoepidermoid carcinoma without NTRK3 rearrangement are 70.22 months and 67.33 months, respectively." (PMID 39376339, 2024).
acinic cell carcinoma (7 papers, 2015 to 2025). "However, carcinomas may frequently display a diffuse oncocytic phenotype, being classified by their characteristic features (e.g., AR-positive salivary duct carcinoma, MEC with MAML2 rearrangements, secretory carcinoma with ETV6 NTRK3 gene fusion, and DOG1- and SOX10-positive acinic cell carcinoma)." (PMID 41440486, 2025).
adenoid cystic carcinoma (7 papers, 2016 to 2025). A malignant tumor arising from the epithelial cells. "In fact, demonstrating a rearrangement of MYB, MYBL1, PLAG1, HMGA2, NTRK3, and a BRAF mutation in the appropriate morphological context is diagnostic of adenoid cystic carcinoma, cutaneous mixed tumor, secretory carcinoma, syringocystadenoma papilliferum, and tubular adenoma." (PMID 35158743, 2022).
bladder cancer (7 papers, 2020 to 2025). "NTRK3 has been associated with tumor mutation burden and immune infiltration in bladder cancer and with TLSs and TILs in gastrointestinal stromal tumors (GISTs)." (PMID 39891665, 2025). "Another study also suggested that NTRK3 was a potential prognostic biomarker associated with tumor mutation burden and immune infiltration in bladder cancer." (PMID 38593276, 2024). "NTRK3 staining was higher in tumor samples than in normal tissue, which was consistent with the result of survival analysis, indicating that high expression of NTRK3 is a risk factor in bladder cancer." (PMID 33894748, 2021). "The network analysis revealed that GNAQ, NTRK3, and IKZF1 are related to UC because they are involved in PI3K/AKT and bladder cancer signaling." (PMID 35864526, 2022). "Moreover, the research indicated that NTRK3 has been proven to be a prognostic biomarker related to TMB and can contribute to the development of bladder cancer immunotherapy." (PMID 36305643, 2022). "Accordingly, NTRK3 may prove to be a novel TMB-related biomarker and contribute to the development of immunotherapy for bladder cancer." (PMID 33894748, 2021).
brain tumor (7 papers, 2020 to 2025). "Typically, NTRK fusion events involve the NTRK1 or NTRK3 genes, whereas NTRK2 mutations are more frequently observed in primary brain tumors." (PMID 40647390, 2025).
medulloblastoma (7 papers, 2013 to 2025). A malignant, invasive embryonal neoplasm arising from the cerebellum. "NTRK3 expression and activation had been shown to trigger apoptosis in medulloblastoma cells." (PMID 35141152, 2021).
mesoblastic nephroma (7 papers, 2005 to 2025). A solid, unencapsulated tumor of the kidney composed of spindle mesenchymal cells that resemble fibroblasts or muscle cells. "For example, in recent years targetable fusions have been identified with high frequency in select pediatric tumors (i.e. NTRK‐fusions in infantile fibrosarcoma and mesoblastic nephromas or ALK/ROS1/NTRK3 fusions in infantile myofibroblastic tumors)." (PMID 33751835, 2021). "The authors also suggest a potential relationship with mixed and classic mesoblastic nephroma, both carrying EGFR‐KDDs, while it is found very rarely in cellular mesoblastic nephroma, which is considered the renal counterpart of IF, characterized by ETV6::NTRK3 fusion." (PMID 40178433, 2025).
breast tumor (6 papers, 2009 to 2022). "The unique ETV6/NTRK3 fusion provides a further way to distinguish SBC from other breast tumors." (PMID 31443715, 2019).
metastatic disease (6 papers, 2020 to 2025). "NTRK fusions discovered involved TRKA (NTRK1) in 4 patients (67%), and TRKC (NTRK3) in 2 patients (33%) with 5 unique fusion partners in primary (3/6, 50%) or metastatic tumor tissue (3/6, 50%)." (PMID 37548775, 2023). "Most patients had metastatic disease (90.6%, 96.3%, resp., p = 0.23) at baseline, and NTRK1 (44.4%, 40.5%, resp., p = 0.70) and NTRK3 (53.0%, 56.8%, resp., p = 0.72) were the most common NTRK gene fusions." (PMID 35406565, 2022).
pancreatic cancer (6 papers, 2019 to 2023). "When applied to a large collection of published pancreatic cancer samples (n = 803), Arriba identified a variety of driver fusions, many of which affected druggable proteins, including ALK, BRAF, FGFR2, NRG1, NTRK1, NTRK3, RET, and ROS1." (PMID 33441414, 2021).
soft tissue tumors (6 papers, 2022 to 2025). "NTRK3 has been found to be frequently involved in gene fusion events underlying soft tissue neoplasms, in which these gene fusions alter kinase activity." (PMID 40700040, 2025). "We described two soft tissue tumors with NTRK3 fusions among 70 soft tissue and bone sarcomas." (PMID 35645621, 2022). "Neurotrophic tyrosine receptor kinase (NTRK)-rearranged spindle cell neoplasms (NTRK-RSCNs) constitute a rare, heterogeneous subset of soft tissue tumors defined by oncogenic fusions involving NTRK1, NTRK2, or NTRK3 genes." (PMID 41409361, 2025). "Neurotrophic tyrosine receptor kinase (NTRK) neoplasms are a rare subset of soft-tissue tumors characterized by gene fusions involving NTRK1, NTRK2, or NTRK3." (PMID 40078480, 2024).
thyroid tumor (6 papers, 2020 to 2025). A benign or malignant neoplasm affecting the thyroid gland. "Afirma XA detected many fusions seen in thyroid neoplasms like PAX8::PPARG, ETV6::NTRK3, CCDC6::RET, NCOA4::RET, STRN::ALK, AGK::BRAF, SND1::BRAF and RBPMS::NTRK3." (PMID 37510219, 2023). "Four out of twenty-six NTRK-rearranged thyroid tumors were negative for Trk expression (15.4%), all carrying the ETV6/NTRK3 fusion." (PMID 35806472, 2022).